NIPSNAP3A (nipsnap homolog 3A)
Synonyms: NipSnap4; TassC; HSPC299; DKFZp564D177; FLJ13953; MGC14553
Tractability: PROTAC: ubiquitination databases record sites on it; its protein half-life has been measured.
Gene: Protein-coding gene on chromosome 9 (104,747,683 to 104,760,138, forward strand). Ensembl gene ENSG00000136783.
Subcellular location: Cytoplasm, cytosol
Gene Ontology:
Molecular function: protein binding
Biological process: mitophagy
Cellular component: mitochondrion; nucleus; cytosol
Genetic constraint (gnomAD): Loss-of-function variants: 24 observed, 28.69 expected, observed/expected ratio (o/e) 0.84, 90% interval 0.61 to 1.18. The upper end of that interval is the gene's LOEUF score, 1.18, which puts it in group 5 of 6, group 1 being the genes least tolerant of losing a copy. Missense variants: 259 observed, 287.45 expected, observed/expected ratio (o/e) 0.9, 90% interval 0.81 to 1. Synonymous variants: 104 observed, 105.54 expected, observed/expected ratio (o/e) 0.99, 90% interval 0.84 to 1.16.
Homologues: Orthologues: chimpanzee NIPSNAP3A (100% identical), mouse Nipsnap3b (83% identical), rat Nipsnap3a (79% identical), mouse Nipsnap3a (76% identical), rat Nipsnap3a (76% identical), tropical clawed frog nipsnap3a (59% identical), zebrafish nipsnap3a (57% identical), Drosophila melanogaster Nipsnap (21% identical), Caenorhabditis elegans K02D10.1 (21% identical). Paralogues in human: NIPSNAP3B (87% identical), NIPSNAP1 (25% identical), NIPSNAP2 (24% identical).
Diseases named in the same sentence as NIPSNAP3A in open-access papers:
NIPSNAP3A is named in the same sentence as 2 diseases in open-access papers, as found by Europe PMC text mining. Sharing a sentence is not in itself a finding about the gene and the disease.
NIPSNAP3A shares sentences with these, for which no sentence is quoted: glaucoma (1 paper); periodontitis (1).